CD86 (CD86 molecule)
Diseases named in the same sentence as CD86 in open-access papers (continued):
Sharing a sentence is not in itself a finding about the gene and the disease.
colon carcinoma (27 papers, 2015 to 2025). "Studies have shown that CD86 gene polymorphisms in miRNA are associated with the risk of malignancies such as pancreatic, cervical, and colon cancers." (PMID 35957907, 2022). "Similar to this antiviral effect, our results suggest that a decrease in CD80/CD86 expression may be associated with CD8+ T cell reduction in the tumor microenvironment of colon tumor growth of S100a4-Cre; Ext1f/f mice." (PMID 36809261, 2023). "Mouse CT26 colon cancer cells and BM-derived dendritic cells (BM-DC) co-cultures on an electrospun fibrous scaffold increased expression of CD86 and major histocompatibility complex Class II." (PMID 33316977, 2020). "Seven checkpoint-related genes (BTLA,CD80, CD86, CTLA4, IDO1, PDCD1LG2, and TIGIT) had decreased expression in the KRAS-mutated group, providing potential opportunities for immunotherapy in colon cancer." (PMID 33254149, 2020). "Colon cancer studies have shown that 48 h after 10 Gy/F radiation, mature CD86+ DCs in tumor tissues significantly increased." (PMID 32942998, 2020). "Some checkpoint-related genes (BTLA, CD80, CD86, CTLA4, IDO1, PDCD1LG2, and TIGIT) had decreased expression in the KRAS-mutated group, providing potential opportunities for immunotherapy in colon cancer." (PMID 33254149, 2020). "MC38 cells are immunogenic and exhibit high expression of the co-stimulatory molecules CD40 and CD86 on the surface of dendritic cells compared with CT26 colon cancer cells; thus, PDT is more effective against MC38 tumor-bearing models compared with CT26 or LLC tumor-bearing models." (PMID 37762216, 2023). "Regarding immune cells in the tumor microenvironment, immunohistochemistry staining of MDSC (CD11b), M2 (CD206) and M1 (CD86) markers in mouse colon tumors showed that the numbers of MDSC- and M2-positive cells decreased remarkably in the metformin-treated mice compared to those in the control mice." (PMID 35740547, 2022). "In our study, we observed differences in the expression levels of various immune checkpoint molecules, including PDCD1, CD86, and CD47, between the high and low-risk groups, indicating that colon cancer patients in the two risk groups may exhibit different responses to ICIs." (PMID 38188686, 2023). "The results showed that PDCD1LG2, ICOS, CD86, CD80, CD48, and CD274 showed a significant exclusion situation from RFX1 expression in colon cancer." (PMID 41425715, 2025). "We analyzed the number of CD86+ (an M1 marker) and CD206+ (an M2 marker) macrophages in colon tumor tissues and revealed that S100A4Smad4-/- mice had reduced M1 phenotype and enhanced M2 phenotype." (PMID 39664586, 2024). "The expression levels of CD80, CD86, and MHC-I on CD11c+MHC-II+ splenic DCs from mice inoculated with murine colon carcinoma cells were lower when compared with normal mice." (PMID 33105813, 2020). "The numbers of CD68+ cells were similar in colon cancer tissues of different AJCC stages but the numbers of CD206+ / CD163+ cells were higher in late stage tumors and the number of iNOS+/CD86+ cells was higher in early stage tumors." (PMID 29368606, 2018). "Heterogeneity of TAM phenotype was described in different tumour types and at different locations of the same tumour e.g. in colon cancer patients, CD80+, CD86+ and HLA-DR+, as well as CD163+, CD86+, CCR2+ cells were described." (PMID 26838097, 2016). "However, higher populations of CD86‐expressing cells and lower populations of CD206‐expressing cells were observed in colonic tumor tissues from mKO mice." (PMID 38308188, 2024). "However, the mechanism by which the macrophage CD86 expression decreased and the macrophage CD206 expression increased in colon cancer is not fully understood." (PMID 37679802, 2023). "In addition, the macrophage CD86 expression was positively correlated with the ILC1 percentage in mouse colon cancer tissues, while the macrophage CD206 expression was negatively correlated with the ILC1 percentage." (PMID 37679802, 2023).
rheumatoid arthritis (26 papers, 2008 to 2025). A chronic, systemic autoimmune disorder characterized by inflammation in the synovial membranes and articular surfaces. "Some studies have found an association between the CD86 gene and several systemic autoimmune disorders, including multiple sclerosis, rheumatoid arthritis, and Graves' ophthalmopathy." (PMID 40520774, 2025). "Logistic regression analysis of association between CTLA-4 rs231775, CTLA-4 rs16840252 and CD86 rs17281995 polymorphisms and the risk of rheumatoid arthritis." (PMID 33604347, 2021). "Some drugs targeting CD86 have been approved for the treatment of rheumatoid arthritis (abatacept, belatacept) and acute graft-versus-host disease (abatacept, belatacept, antithymocyte immunoglobulin)." (PMID 37726845, 2023). "Abatacept, a T-cell selective co-stimulation modulator specifically binding to CD80 and CD86, was approved for use in rheumatoid arthritis (RA) with good efficacy in clinical application." (PMID 35957855, 2022). "The CD80/CD86 levels on the surface of the memory B cells in the blood of 18 patients with rheumatoid arthritis (RA) were detected using immunofluorescence staining." (PMID 32228715, 2020). "RANKL expression was accentuated in CD80+CD86+ B cells, a highly activated B-cell subset more abundantly observed in patients with rheumatoid arthritis." (PMID 26980135, 2016). "Abatacept is the first in a class of agents for the treatment of rheumatoid arthritis (RA) that selectively modulates the CD80/CD86:CD28 co-stimulatory signal required for T-cell activation." (PMID 20398273, 2010). "This work studied the expression of the costimulatory molecule CD86 and the inhibitory receptor for IgG immune complexes FcγRIIb (CD32b), on B cells from rheumatoid arthritis (RA) patients, and the influence of anti-tumor necrosis factor (TNF) therapy." (PMID 20398308, 2010). "Research findings highlight Abatacept’s effectiveness in rheumatoid arthritis (RA) treatment, showcasing its ability to modulate the expression of CD80/CD86 in peripheral blood B cells." (PMID 38398810, 2024). "For rheumatoid arthritis (RA), three JAK inhibitors and a range of bDMARDs are approved, including those targeting TNFα, IL-6, IL-1β, B cells (CD20), and T cells (CD80/CD86)." (PMID 34290741, 2021). "Abatacept (ABA) is a fusion receptor protein containing the CTLA-4 domain that prevents the activation of naïve T cells by binding the CD80 and CD86 molecules expressed on the surface of dendritic cells, indicated for the treatment of moderate to severe rheumatoid arthritis (RA)." (PMID 27098382, 2016). "It is believed to be effective in the treatment of rheumatoid arthritis by inhibiting costimulation of T cells via blocking CD28–B7 interactions as CTLA-4 binds to both B7.1 (CD80) and B7.2 (CD86)." (PMID 26290328, 2015). "The in vitro treatment of peripheral blood mononuclear cells of patients with rheumatoid arthritis with HSP70 induces the production of IL-10, and Mycobacterium tuberculosis HSP70 (mtHS70) blocks the maturation of bone marrow precursors that fail to express MHC class II and CD86." (PMID 36830641, 2023). "In vitro treatment of peripheral blood mononuclear cells of patients with rheumatoid arthritis with HSP70 induce the production of IL-10 and Mycobacterium tuberculosis HSP70 (mtHS70) blocks the maturation of bone marrow precursors that fail to express MHC class II and CD86." (PMID 36830641, 2023). "Analyzing CD86 expression on B cell subtypes might be useful knowing that the mutual numbers of and function of SM, NSM and DNM might differ depending on disease activity in rheumatoid arthritis." (PMID 32197584, 2020). "The biologic abatacept has traditionally been used for the treatment of rheumatoid arthritis (RA), where it acts as a T-cell inhibitor by binding to CD80 (B7-1) and CD86, thus blocking the costimulatory receptor CD28." (PMID 26490951, 2016).
colorectal cancer (24 papers, 2004 to 2025). A primary or metastatic malignant neoplasm that affects the colon or rectum. "Multiplex immunofluorescence (mIF) quantification revealed significantly increased densities of both CD68+CD86+ and CD68+CD163+ TAMs, and a higher CD68+CD163+/CD68+CD86+ ratio in colorectal cancer (CRC) (all P < 0.001)." (PMID 41395618, 2025). "This study investigated the association between Helicobacter pylori (H. pylori) infection and the expression of CD163+ and CD86+ tumor-associated macrophages (TAMs) in colorectal adenoma (CRA) and colorectal cancer (CRC) tissues." (PMID 41395618, 2025). "CD86+ B cells, a physiologic B cell subset, have been shown to be increased in the tumor microenvironment of gastric cancer, colorectal cancer, and head and neck squamous cell carcinoma patients." (PMID 38136327, 2023). "We investigated the stromal CD86+TAM/CD163+TAM (CD86/CD163) ratio as a novel prognostic biomarker for stage II-III colorectal cancer (CRC)." (PMID 34512652, 2021). "In parallel, elevated expression of CD86, correlates with clinical data that most macrophages distributed along the invasive margin of colorectal carcinoma are CD86+." (PMID 26838097, 2016). "In addition, pDCs were also found to moderately express CD86, and monocytes in colorectal cancer also moderately expressed CD86." (PMID 39120585, 2024). "Another research work has demonstrated that the CD86/CD163 ratio may be used for individualized assessment of recurrence and mortality risk in colorectal cancer patients." (PMID 38136305, 2023). "For example, in colorectal cancer, the abundance of macrophages expressing high levels of CD86 and low levels of CD163 could be used as predictor of prognosis." (PMID 38140397, 2023). "In colorectal cancer, the infiltration of CD86+ TAMs indicated a favorable prognosis." (PMID 26938527, 2016). "Immunohistochemistry for CD68 (macrophage marker), CD86 (M1 macrophage marker) and CD206 (M2 macrophage marker) was performed in biopsy samples from colorectal carcinoma resections." (PMID 24901518, 2014). "Transcripts specific to co-stimulatory molecules (CD80 and CD86), HSP60, MHC peptides, pro-inflammatory cytokine receptors, Perforin 1 and Caspase 9 were amongst those that were up-regulated in MSI-H colorectal cancers." (PMID 15298707, 2004). "Expressions of CD68, CD86 and CD163 were investigated by immunohistochemistry (IHC) and immunofluorescence (IF), and the correlation between the expression of CD86 and CD163 was calculated in colorectal cancer tissues from 64 CRC patients." (PMID 34964155, 2022). "Based on these data and the correlations with cytokine levels, it can be concluded that CD25, CD80, CD86, CD274 and CD279 glycoproteins combined with specific plasma levels of IL-1β, IL-2, IL-15 and TGFβ could represent potential biomarkers for colorectal cancer." (PMID 39456247, 2024). "In the results of phenotype analysis by flow cytometry, colorectal cancer cells expressing higher MTA1 promoted the polarization of macrophages to the CD206+ phenotype while inhibiting CD163+ polarization without affecting the polarization of the CD86+ phenotype." (PMID 35350571, 2022).
influenza (23 papers, 2007 to 2025). An acute viral infection of the respiratory tract, occurring in isolated cases, in epidemics, or in pandemics; it is caused by serologically different strains of viruses (influenzaviruses) designated A, B, and C, has a 3-day incubation period, and usually lasts for 3 to 10 days. "High doses of MMF/MPS inhibit influenza-induced CD86 and human leucocyte antigen-DR expression on B cells, resulting in a poor response to influenza vaccine." (PMID 40006735, 2025). "CD86 overexpression was primarily observed in influenza NP cells, implying that CD86 upregulation is highly infection‐dependent." (PMID 38045624, 2023). "Conditional deletion of CD80 and CD86 in B cells also reduced anti-influenza IgG antibody production in an infection model in vivo." (PMID 32228715, 2020). "Surface expression of CD83, CD86 and HLA-DR in all influenza nanoparticle construct-treated conditions were significantly higher (P <0.05) than that of all soluble protein conditions at both time points." (PMID 32760143, 2020). "The elevated CD28 levels on lung ILC1s indicate a potential role for the CD28-CD80/CD86 axis leading to improved ILC1s responsiveness during influenza infection." (PMID 31440243, 2019). "Preferential induction of CD86 over CD80 in vivo has been demonstrated in a mouse model for influenza infection, in which type I IFN-mediated signals were responsible for upregulation of CD86 in B cells." (PMID 24472094, 2014). "The role of CD86 co-stimulation and Treg function during recovery from influenza infection is discussed." (PMID 25144228, 2014). "Like in NP-OVA immunized mice and in human tonsils, we saw more CD83 and CD86 on WT CXCR4lo centrocytes than on CXCR4hi centroblasts during influenza infection." (PMID 24184055, 2013). "Delays in the upregulation of CD83 and CD86 were seen, compared to Influenza, which is a robust activator of pDCs." (PMID 22693567, 2012). "We see a low CD86 upregulation following both poly(I:C) stimulation and infection with a NS1-deficient strain of influenza (ΔNS1/PR8)." (PMID 20661430, 2010). "Both subsets upregulated the expression of CD86 upon influenza infection and presented to CD8 T cells." (PMID 19784375, 2009). "Indeed, pre-vaccination expression of costimulatory molecules, CD80 and CD86 on TLR-activated monocytes from elderly and young HIV-uninfected adults was shown to associate with vaccine responses to influenza." (PMID 33868267, 2021). "This dysregulation of TNF-α and IL-6 vs. IL-10 response to influenza vaccination has been linked to the downregulation of the expression of the costimulatory molecules CD80 and CD86 by activated monocytes as a predictor of the antibody response to influenza vaccination." (PMID 28769922, 2017). "Recent work in a mouse model of acute influenza infection has demonstrated that MHC class I, CD80, and CD86 are all required to maintain PD-1+ TRM cells." (PMID 36189800, 2022). "Expression of the T cell stimulatory molecules, HLA-DR and CD86, as well as the inhibitory PDL1 protein was induced on influenza-infected macrophages." (PMID 25775126, 2015). "In the influenza model, CD80 and CD86 have been analyzed primarily in their capacity to support the induction of pro-inflammatory T effector responses and the expression of pro-inflammatory mediators by the T effector cells." (PMID 25144228, 2014). "By day 7, expression of Ccl3, Cxcl9, Cd86, Il-6, Cd80, and Cxcl11 remained elevated in young adult lung in response to H1N1, while expression of Ccl5, Ccl4, and Cd40 remained elevated in response to either strain of influenza." (PMID 34829979, 2021). "In addition to B7+antiCD3 surface-engineered particle preparations derived from the three infectious agents (HIV-1, HSV-2, and Influenza), individual antiCD3 and CD80/CD86 (B7) costimulatory engineered particle preparations were also produced and tested." (PMID 17504532, 2007).
influenza (continued). "For example IL-2,a critical regulator of Treg viability and maintenance, could potentially help sustain Treg responses in the late phase of influenza infection, with CD4+ T effector cells serving as a source of IL-2 through a CD86 engagement dependent mechanism." (PMID 25144228, 2014). "By studying the expression of MHCII, CD86 and the potential of cDCs to present viral derived antigen to CD8 T cells, we found little evidence for altered DC accessory function when NK1.1-positive cells were depleted during influenza, lending little support to the former theory." (PMID 19784375, 2009). "We also assessed AT2s for CD80, CD86, and ICAM-1 expression and found that AT2s expressed ICAM-1, but not CD80 or CD86, both at homeostasis and after influenza infection." (PMID 34183650, 2021). "By in vivo antibody-mediated blockade of CD80 or CD86 after virus clearance, we found that engagement of CD86 (but not CD80) was required for optimal recovery after influenza infection." (PMID 25144228, 2014).
gastric cancer (20 papers, 1995 to 2025). A primary or metastatic malignant neoplasm involving the stomach. "This would be reminiscent of data obtained on Epstein-Barr Virus (EBV), where infection changes the ability of exosomes purified from gastric cancer cell lines to mature MDDCs, leading to a defect in CD86 upregulation and reduced tumor immunity." (PMID 39283919, 2024). "As early as 1998, Japanese scholars discovered that CD86 was highly expressed in various gastric cancer cell lines." (PMID 38348052, 2024). "For example, CD80 and CD86 are markers of M1 macrophages, which can inhibit tumor growth of gastric cancer." (PMID 37274740, 2023). "PDTC also reduced the upregulation of CD86+ macrophages induced by gastric cancer cells overexpressing CDK5RAP3." (PMID 35999359, 2023). "The neutralizing antibodies against IL4 and IL10 also reduced the upregulation of CD86+ macrophages induced by the overexpression of CDK5RAP3 in gastric cancer cells." (PMID 35999359, 2023). "The proportion of CD86+ TAMs was increased under coculture conditions with gastric cancer cells overexpressing CDK5RAP3." (PMID 35999359, 2023). "The fraction of monocyte-derived DCs positive for the maturation marker CD86 was significantly suppressed when incubated with exosomes from EBV-infected gastric cancer cell lines." (PMID 33198173, 2020). "The ratios of CD86 positive cells were 15.0% and 12.3% when incubated with the gastric cancer exosomes in MKN74 + EBV and SNU719, respectively." (PMID 33198173, 2020). "Dendritic cells expressing Langerin, CD1a, S100, CD83, CD86, and BDCA-2 were detected in gastric cancer tissue by immunohistochemical analysis." (PMID 33198173, 2020). "Overlap analysis with genes that co-expressing in 381 gastric cancer tissues and 37 gastric cells demonstrates that various immune related genes such as CCL18, TLR8, C3AR1, CYSLTR2 and CD86 are positively correlated with CD163." (PMID 29152078, 2017). "Results showed higher staining of CD86 (118/157, 75%), ICOSLG (122/157, 77%), B7-H3 (138/157, 88%), B7-H7 (138/157, 88%), and B7-DC (104/157, 66%) and overall lower staining of CD80 and B7-H6 in gastric cancer tissues." (PMID 32025206, 2020). "Furthermore, results from Protein Atlas database validate immune molecules including CD86, CD209, C3AR1, CLEC4D, CLEC7A and CYSLTR2 are positive in gastric cancer cells." (PMID 29152078, 2017). "We observed that 5-FU-resistant gastric cancer cells were more effective than 5-FU-sensitive gastric cancer cells in skewing macrophages to M2 polarization, characterized by up-regulated expression of CD163, CD206, IL-10, Arg-1 and VEGF-A and down-regulated expression of CD86, TNF-α and IL-12." (PMID 36151545, 2022).